TNF (tumor necrosis factor)
Diseases named in the same sentence as TNF in open-access papers (continued):
Sharing a sentence is not in itself a finding about the gene and the disease.
Sepsis (continued). "This is mediated via tumor necrosis factor α (TNF-α) and other inflammatory mediators released by Kupffer cells during sepsis and/or inflammation related to native disease or surgery." (PMID 23363993, 2012). "In CLP mice, levels of pro-inflammatory factors IL-6 and TNF-alpha were significantly increased, while the anti-inflammatory factor IL-10 was decreased in sepsis in both the plasma and peritoneal cavity 24 h after surgery." (PMID 22590504, 2012). "TAT complex levels were increased in culture supernatants from sepsis neutrophils and control neutrophils treated with sepsis serum or TNF-α, IL-1β and G-CSF (Fig. 4iii)." (PMID 23029002, 2012). "In this study, we demonstrated a significant increase in gene production of proinflammatory cytokines, including TNF-α and IL-1β, in brain tissues of mice at 12–24 h after sepsis induction by CLP." (PMID 23236515, 2012). "Instead of LPS we used TNF alpha as a more selective and efficient pro-inflammatory stimulus for sepsis according to our established protocols, respectively in an inflammatory model with endothelial cells having been published already." (PMID 22973876, 2012). "“Cardiosuppressive cytokines,” the definition of which is based on their ability to disrupt normal contractile function of normal CMs, have been described in patients with sepsis, and include IL-6, TNF-α, and IL-1β." (PMID 23233853, 2012). "This proinflammatory cytokine works together with TNF-α to propagate the hyperimmune response of sepsis." (PMID 23251827, 2012). "The serum concentration of TNF-α in severe sepsis patients with AA+AG genotypes was significantly higher than that of patients with GG genotype (550.4±73.6 pg/mL vs. 488.0±68.5 pg/mL, P = 0.001)." (PMID 23029405, 2012). "■ TNF-α, an early mediator in the systemic inflammatory response to infection, is a therapeutic target in sepsis." (PMID 22340283, 2012). "IL-6 is an early mediator and has a longer half-life period than TNFα and IL-1β and that intrinsic property makes it possible to use IL-6 as a marker of sepsis and SIRS." (PMID 24049646, 2012). "Interleukin-2 is a proinflammatory cytokine as interleukin-6, tumor necrosis factor-α, and interferon-γ, which participate in the inflammatory response regulation in sepsis." (PMID 22645477, 2012). "Sepsis starts as a process of system inflammation mediated by pro-inflammatory cytokines/chemokines including TNF-α, IL-1, IL-6, MIP-1α, MCP-1, IFN-γ, and IL-17 as well as anti-inflammatory cytokines, e.g. IL-10." (PMID 23056325, 2012). "AZD9773 is an ovine-derived, polyclonal, anti-human TNF-α Fab preparation in development for the treatment of patients with severe sepsis and septic shock." (PMID 22340283, 2012). "Cytokines and chemokines, particularly TNF-α and IL-6, are considered the first line biomarkers that drive the dynamic process of sepsis." (PMID 23049598, 2012). "Compound 6e with a statistically significant improved effect on reduction of IL-6 and TNF-α secretion upon E. coli inoculation as compared to ketamine is a good candidate for the treatment of sepsis." (PMID 22664467, 2012). "TNFα is released first when sepsis occurs and leads to cleavage of the nuclear factor κB (NF-κB) inhibitor." (PMID 22564340, 2012). "The pathogenesis of sepsis is rather complex, but is partly mediated by endotoxin, which stimulates macrophages/monocytes to sequentially release early (e.g., TNF, IL-1, IFN-γ) and late (e.g., HMGB1) proinflammatory mediators." (PMID 23193422, 2012). "The significant synthesis of TNF-α is responsible for the severe sepsis and recruitment of neutrophils to the infectious focus." (PMID 22655058, 2012). "TNF-α injection into animals has been shown to trigger a sepsis-like syndrome including hypotension, activation of the clotting cascade, significant organ dysfunction, and even death." (PMID 23251827, 2012).
Sepsis (continued). "TNF, being an endogenous pyrogen, is able to induce fever, to induce apoptotic cell death, to induce sepsis (through IL1 & IL6 production), to induce cachexia, induce inflammation, and to inhibit tumorigenesis and viral replication." (PMID 22754316, 2012). "TNF-α is a major pro-inflammatory molecule activated in experimental models of sepsis and is considered one of the main mediators of AKI." (PMID 22655058, 2012). "Given its role as an early mediator of the inflammatory response, TNF-α is an appropriate target for the treatment of sepsis." (PMID 22340283, 2012). "Accumulating evidences indicate that myocardial TNFα (versus systemically) is an autocrine contributor to myocardial dysfunction and apoptosis in sepsis and chronic heart failure." (PMID 22761733, 2012). "The primary objective of this study was to determine the safety and tolerability of AZD9773, an ovine, polyclonal, anti-human TNF-α Fab preparation, in patients with severe sepsis." (PMID 22340283, 2012). "Previous studies with MyD88−/− mice showed improved renal function of these animals after sepsis and also decreased serum levels of TNF compared with controls." (PMID 22655058, 2012). "In a Phase II study in patients with severe sepsis, CytoFab reduced plasma TNF-α and IL-6 levels and increased the number of ventilator- and intensive care unit (ICU)-free days compared with placebo." (PMID 22340283, 2012). "Cardiomyocyte (CMs) isolated from wild mice undergoing sepsis produced high levels of IL-6, TNF-α, IL-1β, MIP-1α, MIP-2, MCP-1, and KC, while CMs from C5L2-deficient mice secreted significant low level of the inflammatory mediators." (PMID 23233853, 2012). "IL-6 is one of the first acute phase cytokines released in sepsis/endotoxemia and is followed by increases in the levels of IL-1β, IL-8, TNF-α and IL-10." (PMID 23078757, 2012). "The proinflammatory cytokine TNF-α is an essential component in the host immune response to infection and has been widely reported to be an important mediator in severe sepsis and septic shock." (PMID 23029405, 2012). "As sepsis progresses, complement activation by considerable release of cytokines (TNF-α, IL-6, IL-10, etc.)produced enormous components, such as C3a, C4a, and C5a, and further consumed the pool of complement C3 and C4." (PMID 23091606, 2012). "A hypodynamic state of sepsis in humans can occur in cases of hypovolemia or cardiac depression due to cytokines (tumor necrosis factor (TNF)-α, interleukin (IL)-1β, IL-6, and others)." (PMID 22587828, 2012). "We have proceeded to show that stimulation of NOD1 in human endothelial cells induces multiple chemokine and cytokine response genes that are implicated in sepsis including CXCL6, CXCL8, IL1-β and TNFα." (PMID 22870324, 2012). "Proinflammatory cytokines play a critical role in ALI and ARDS: persistently elevated levels of proinflammatory cytokines such as TNF-α and IL-6 are associated with worse outcome in patients with ALI or sepsis." (PMID 23199346, 2012). "The levels of TNFα were also increased in sepsis, with a trend to lower levels in Mttp-IKO septic mice." (PMID 23145105, 2012). "WMI was increased in infants with clinical early-onset sepsis and higher plasma levels of IL-8, IL-6, and TNF-α." (PMID 22530124, 2012). "In conclusion, the data support further assessment of this ovine-derived, anti-TNF-α antibody fragment in patients with severe sepsis." (PMID 22340283, 2012). "Tumor necrosis factor-alpha (TNF-α), an early mediator in the systemic inflammatory response to infection, is a potential therapeutic target in sepsis." (PMID 22340283, 2012). "These include both early- and late-onset sepsis, as well as NEC and are generally associated with high plasma levels of IL-6, IL-8, and TNF-α." (PMID 22530124, 2012). "Sepsis induced by CLP resulted in a significant up-regulation of cerebral expression of TNF-α and IL-1β mRNA (n = 5)." (PMID 23236515, 2012).
Sepsis (continued). "Subsequent studies indicated TNF-α and IL-1β as the pivotal mediators inducing cardiac depression in sepsis and other disease conditions." (PMID 22577249, 2012). "PD-L1 blockade significantly improved survival of CLP mice by preventing sepsis-induced depletion of lymphocytes, increasing TNFα and IL-6 production, decreasing IL-10 production, and enhancing bacterial clearance." (PMID 21349174, 2011). "TNF-α and IL-6 have been considered to be the primary mediators of sepsis, and a positive correlation has been found between serum IL-6 and TNF-α levels and multiple organ failure." (PMID 21931850, 2011). "During endotoxemia or sepsis, multiple early cytokines (such as TNF-α and IFN-γ) are responsible for counter-regulating hepatic fetuin-A expression, thereby reducing circulating fetuin-A levels." (PMID 21347455, 2011). "Previous studies have described linear relationships between plasma ANGPT2 and TNFα concentrations in humans with endotoxemia and sepsis." (PMID 21829546, 2011). "Listeriosis in patients treated with TNF inhibitors can present as septic arthritis, meningitis or sepsis." (PMID 22081766, 2011). "At 6 hours after sepsis, the response to LPS induced IL-8 and TNF-α release were modulated downward in SCD-C animals versus SCD-H." (PMID 21533222, 2011). "IL-1, endotoxins and particularly TNF-α, which are increased in states of sepsis, can stimulate CNP release from isolated endothelial cells and in this way regulate local vascular tone." (PMID 21281508, 2011). "The pattern of production of IL-1β is different from that with TNFα, as IL-1β is being down-regulated both in severe sepsis and in uncomplicated sepsis, while TNFα production is sustained in this last category of patients." (PMID 21244670, 2011). "In a mouse model of sepsis, IL-32 was shown to potentiate peritonitis-induced elevations in serum levels of TNF-α and IL-1β, and overexpression of the IL-32β isoform led to reduced time to death." (PMID 21649914, 2011). "Those Ms from patients with high levels of LPS (CF and sepsis) were unable to produce significant TNFα quantities after ex vivo LPS challenge." (PMID 22216320, 2011). "After induction of sepsis, significantly higher TNF-α levels were seen in WT mice than in plg-/- mice at all 4 time points studied." (PMID 21931850, 2011). "Depending on this view, exogenous administration of rmMFG-E8 attenuated inflammation by reducing pro-inflammatory cytokines, TNF-α, IL-6 and IL-1β in sepsis as well as other diseases where LPS-TLR4 signaling is predominant." (PMID 22114683, 2011). "TNF-α is a cytokine secreted by macrophages in response to inflammatory stimuli and is involved in immune regulation and inflammation as well as in sepsis, apoptotic cell death and cancer." (PMID 22081766, 2011). "To investigate the potential role of PD-1/PD-L1 on T-cell apoptosis in sepsis, we induced the apoptosis under stimulation with exogenous recombinant TNFα or anti-CD3 and anti-CD28 ligation." (PMID 21349174, 2011). "In seeking anti-inflammatory supplements to restrain TNF production, we found the ethyl pyruvate and alpha7nAChR agonists effectively inhibit TNF production in sepsis and hemorrhage." (PMID 20628562, 2010). "Serum leptin increases in SIRS and sepsis and is strongly related to circulating levels of TNF-α, IL-6." (PMID 20230641, 2010). "Plasma TNFα was below the lower limit of detection in the majority of patients in both the sepsis and control groups." (PMID 20482750, 2010). "Since TNF-α is considered to play a key role in the pathogenesis of sepsis and septic shock, TNF-α is an important component of the pro-inflammatory cytokines during the early stages of septic shock." (PMID 23554654, 2010). "Clinical and experimental studies suggest that cytokines, especially TNFα, IL-1β and IL-6 appear to play a pivotal role in mediating the hemodynamic effects and the release of cardiac troponin in patients with severe sepsis and septic shock." (PMID 20140242, 2010).
Sepsis (continued). "Ethyl pyruvate, an anti-oxidant that inhibits HMGB1 secretion from macrophages, can be added a day after TNF production to reverse the established sepsis." (PMID 20628562, 2010). "In this study, we showed that OMVs derived from intestinal E. coli are causative microbial signals in the pathogenesis of systemic inflammatory response syndrome (SIRS) and sepsis-induced lethality, through the systemic induction of TNF-α and IL-6." (PMID 20596524, 2010). "Due to its multiple functions in immunological activity, TNF-α plays a critical role in several conditions that involve systemic inflammatory responses, such as sepsis and toxic shock." (PMID 20967289, 2010). "For this reason, culture models of sepsis have been developed which utilize incubation of healthy cells with bacteria, endotoxin (LPS), or exogenous inflammatory mediators such as TNFα or IL-6." (PMID 20593014, 2010). "• Anti-PD-L1 antibody administration prevented sepsis-induced depletion of lymphocytes, increased TNF-α and IL-6 production, decreased IL-10 production, and enhanced bacterial clearance." (PMID 21118528, 2010). "Progression from sepsis to septic shock coincides with the increase in circulating levels of proinflammatory cytokines such as TNF, interferon gamma, IL-1, and IL-6." (PMID 20628562, 2010). "Many published works have focused on the role of soluble tumor necrosis factor-α (TNF-α) as an important cytokine in inflammatory states including sepsis." (PMID 20230641, 2010). "It has been found to be a very potent immunostimulating agent by priming macrophages to produce cytokines, like TNF-a and IL-6 in blood of healthy humans as well as in blood of immunosupressed patients with sepsis and after cardiopulmonary bypass." (PMID 20604971, 2010). "We next identified, in each cohort, genes that are well known in the sepsis literature (for example, tumour related factor (TNF), interleukin (IL)-1, IL-8, IL-10 and TGF-beta)." (PMID 21190579, 2010). "Plasma TNFα levels in sepsis patients in this study were relatively low, with only 1 of 69 sepsis patients having TNFα levels of 40 pg/ml or more, similar to the low levels reported in other sepsis studies." (PMID 20482750, 2010). "Septic shock is a severe sepsis due to excessive release of proinflammatory cytokines such as TNFα and IL-12, which then lead to vasodilation, increased vascular permeability, hypotension, multiple organ failure and ultimately shock and death." (PMID 20231889, 2010). "It is known that the persistence of TNF-α and IL-6 in the serum peak levels of cytokines reveals the onset of sepsis and predicts poor outcome in septic patients." (PMID 20230641, 2010). "TNFα and IL-1 are prototypic pro-inflammatory mediators that have been reported to have a prognosis value in sepsis, even if their clinical relevance was also questioned." (PMID 20076757, 2010). "Anti-PD-L1 antibody administration prevented sepsis-induced depletion of lymphocytes, increased tumor necrosis factor (TNF)-α and interleukin (IL)-6 production, decreased IL-10 production, and enhanced bacterial clearance." (PMID 21118528, 2010). "Pro-inflammatory cytokine production such as TNF-α and IL-1β in the early phase of sepsis has the potential to activate NF-κB and other transcription factors that are key in the reactivation of CMV from latency." (PMID 19442306, 2009). "The impairment of hepatocellular function observed in early sepsis appears to be due to upregulation of proinflammatory cytokines such as TNF-α." (PMID 19430535, 2009). "A serial estimation of IL-6 and TNF-α and their correlation with mortality in sepsis were done in elderly patients." (PMID 19881187, 2009). "TNF-α is known to stimulate the production of several cytokines including IL-8 and propagate the cascade of phenomena in severe sepsis." (PMID 20130823, 2009). "Programmed cell death of T-cells in sepsis is mediated by a number of stimuli (e.g. Fas ligand, TNF-α or steroids) and can proceed via different apoptotic pathways." (PMID 19740426, 2009).
Sepsis (continued). "This is accompanied by a reduction in the pro-inflammatory mediators IL-1β, IL-6 and TNF-α, as well as a decrease in NF-kB binding activity, thereby inhibiting an overwhelming inflammation response to sepsis." (PMID 19196475, 2009). "For example, while neutralization of ether TNF-α or IL-1β has little effect on mortality in humans or in mice subjected to lethal polymicrobial sepsis via Cecal Ligation and Puncture (CLP), combined neutralization does improve survival in CLP." (PMID 19672303, 2009). "Increased portal norepinephrine in sepsis trigger hepatic release of TNF-α, which is in turn a prerequisite for venolar temporary leukocyte adhesion." (PMID 19594914, 2009). "The importance of TNF-α for sepsis onset is supported by a previous study of our group that demonstrated an important role for TNF-receptor 1 in the septic course." (PMID 19594900, 2009). "As it is well known that IL-10 and TNF-alpha play an important role in immune response and are dysregulated in sepsis patients, we checked by using an additional target prediction program (RNA22) to identify possible regions of interaction with miR-150." (PMID 19823581, 2009). "In contrast to the results obtained at 48 hours, represented by the suppression of TNF-α in the vehicle-treated sepsis group in both tissue types, expression of this group is strongly up-regulated 96 hours after sepsis induction in liver tissue." (PMID 19594900, 2009). "The intestine is an important source of NE release in the early stage of cecal ligation and puncture (CLP)-induced sepsis in rats, which then stimulates TNF-α production in Kupffer cells (KCs) through the activation of the α2-AR." (PMID 19430535, 2009). "Cytokine profiling for TNF-α and IL-6 level in elderly patients with sepsis helps in prognosticating the outcome." (PMID 19881187, 2009). "Rodents subjected to stimuli that are known to induce a high intracellular level of HSPs and subsequent induction of otherwise lethal sepsis exhibited attenuated release of TNF-α and IL-6 and reduced mortality." (PMID 19173710, 2009). "This is characterized by an initial burst of pro-inflammatory cytokines, such as IL-6, TNF-α and IL-1β, which in controlled settings, can recapitulate many of the clinical findings of sepsis." (PMID 19672303, 2009). "• Pituitary mRNA expression of proinflammatory TNF and IL-6 is upregulated during experimental sepsis." (PMID 19196477, 2009). "Immune reactivity in the later phases after sepsis onset, in particular TNF-α expression, is typically depressed." (PMID 19594900, 2009). "Rats receiving either 1,600 kDa HA or 35 kDa HA pretreatment showed less MIP-2 and TNFα production at the mRNA and protein level compared with rats with sepsis." (PMID 18691420, 2008). "In animal models of sepsis, pentoxifylline, a methylxanthine deriviative, inhibits production of Tumor Necrosis Factor (TNF), preserves micro-vascular blood flow, prevents circulatory failure and intestinal vaso-constriction and improves survival." (PMID 19063731, 2008). "Sepsis starts as a process of intravascular inflammation mediated by pro-inflammatory cytokines/chemokines including TNF-α, MIP-1α, MCP-1, IFN-γ, and IL-17 as well as anti-inflammatory cytokines, e.g. IL-10." (PMID 18937852, 2008). "The sustained high levels of TNFα in the LPS group is consistent with observations in patients with sepsis, in whom persistent high levels of TNFα correlates with severity of illness." (PMID 18702832, 2008). "Sepsis enhanced the transcription of several pro- and anti-inflammatory cytokines and chemokines including tumor necrosis factor alpha, interleukin-1 beta, transforming growth factor beta, and monocot chemoattractant protein 1 in the cerebrum." (PMID 18793399, 2008). "Studies have also shown that circulating concentrations of TNF-α, IL-1β, and IL-6 increase significantly in the early, hyperdynamic stage of sepsis and remain elevated in the late, hypodynamic stage of sepsis." (PMID 18680601, 2008).